JAK2 (Janus kinase 2)
Diseases named in the same sentence as JAK2 in open-access papers (continued):
Sharing a sentence is not in itself a finding about the gene and the disease.
liver cancer (continued). "In the current study, FPHPE was found to inhibit the growth of HCC by reducing the phosphorylation of JAK2 and STAT3 and preventing STAT3 from going into the nucleus, suggesting that FPHPE alleviated the inflammatory signaling of liver cancer by targeting the JAK2/STAT3 pathway." (PMID 41200213, 2025). "Besides, accumulating evidences have demonstrated that paeonol and forsythoside A, the effective components in JJJG, can act on the key pathological mechanism of (IL-6, TNF-α, IL-1β)/JAK2/STAT3/VEGF in the treatment of liver cancer and acute lung injury." (PMID 39494342, 2024). "The objective is to explore whether K73-03 could induce apoptosis or autophagy in liver cancer cells and clarify its relationship with JAK2 / STAT3 signaling pathway or other possible mechanisms." (PMID 38185661, 2024). "A second report documented the inactivation of the JAK2/STAT3 pathway in a liver cancer model, in a similar fashion: a curcumin analog, GL63, contributes to a decreased expression of circZNF83, a sponge for miR-324-5p, whose target is cyclin-dependent kinase 16 (CDK16)." (PMID 37376060, 2023). "Perhaps Jun and Jak2 changed methylations are potential biomarkers for predicting liver cancer." (PMID 36594057, 2023). "Finally, the effect of the JAK2 inhibitor lestaurtinib on the viability of liver cancer cells was evaluated by pharmacological experiments." (PMID 35646925, 2022). "These indicate that regulating IL-6/JAK2/STAT3 signaling pathway may be a therapeutic strategy for liver cancer." (PMID 36591515, 2022). "Simialrly, miR-337-3p inhibited liver cancer cell progression by targeting JAK2." (PMID 33896365, 2021). "XCHD inhibits the growth of liver cancer cells via the JAK2/STAT3 pathway." (PMID 33029173, 2020). "Moreover, the proliferation rates of liver cancer cells were also greatly suppressed by treatment with the JAK2 inhibitor and IL6 neutralizing antibody." (PMID 29722127, 2018). "In addition, the IL6/JAK2/STAT3 signalling pathway was demonstrated to be involved in CD90+ liver cancer stem cell function modulation in our assays." (PMID 29722127, 2018). "IL-6, phosphorylated JAK2 and phosphorylated STAT3 protein levels were significantly increased in liver cancer cells." (PMID 36591515, 2022). "The levels of IL-6, phosphorylated JAK2 and phosphorylated STAT3 were significantly increased in liver cancer cells." (PMID 36591515, 2022). "ZZXJD induced autophagy and apoptosis of liver cancer cells via inhibiting AKT/mTOR signaling pathway and JAK2/STAT3 signaling pathway, thereby affecting the growth and survival of liver cancer cells." (PMID 35432564, 2022). "In summary, these results suggest that, in liver cancer cells, DNMT3a upregulation promotes SOCS3 promoter methylation and suppresses SOCS3 expression, which further activates JAK2/STAT3 signaling pathway." (PMID 33234142, 2020). "A recent study has shown that forced expression of ISG20 promotes metastases and angiogenesis via the IL-8/p-JAK2/p-STAT3 signalling pathway, both in liver cancer cell lines and in animal models, suggesting a pro-tumour role of ISG20." (PMID 29963243, 2018). "For more information about the downstream pathways associated with CD90‐mediated stem cell functioning in liver cancer cells, the IL6/JAK2 signalling components and STAT3 phosphorylation were further analysed in liver cancer cells 97L and Huh7." (PMID 29722127, 2018). "The stem cell properties of CD90+ liver cancer cells are regulated by the downstream SHH/Gli and IL6/JAK2/STAT3 signalling pathways." (PMID 29722127, 2018). "Application of the JAK2 inhibitor AZD1480 and IL6 neutralizing antibody showed the CD90 and SHH/Gli‐regulated liver cancer stem cell functions were mediated by the IL6/JAK2/STAT3 pathway." (PMID 29722127, 2018). "In contrast, knockdown of Gli1 and Gli3 significantly down‐regulated IL‐6, phosphorylated JAK2, phosphorylated STAT3protein abundances in CD90+ 97L liver cancer cells." (PMID 29722127, 2018).
liver cancer (continued). "At present, YWHAZ, JAK2, PDK1 and YAP1 have been identified as cancer relevant direct miR-375 targets in human gastric, esophageal and liver cancer using Luciferase reporter assays." (PMID 24892549, 2014). "Hence, it is necessary to further study the relationship between JAK2/STAT3 pathway and inhibition of K73-03 on liver cancer cells." (PMID 38185661, 2024). "Through the preliminary RNA-seq analysis, combined with the Western blot and qRT-PCR detection of this experiment, the research team found that the prescription ZZXJD inhibited the proliferation of liver cancer cells and was related to the PI3K/Akt/m TOR and JAK2/STAT3 signaling pathways." (PMID 35432564, 2022). "Momelotinib inhibits the phosphorylation of Jak2 and STAT3, and the inhibitory effect of this phosphorylation may affect the subsequent molecular signal transmission of liver cancer cells." (PMID 34199353, 2021). "Functional analysis was conducted by siRNA‐mediated CD90, Gli1 and Gli3 gene knockdown, SHH treatment and application of the JAK2 inhibitor AZD1480 and IL6 neutralizing antibody in CD90+ liver cancer stem cells, followed by cell proliferation, migration, sphere formation and tumorigenicity assays." (PMID 29722127, 2018). "To examine whether ATO combined with CT–induced liver cancer cell apoptosis was related to the JAK/STAT3 signaling pathway, we detected the expressions of phosphorylated-JAK2 and phosphorylated-STAT3-Tyr705." (PMID 28187727, 2017). "We were not able to detect JAK2 phosphorylation in these liver cancer cell lines and in SNU387 cell line, the phosphorylation of STAT3 (Ser727) could not be detected." (PMID 20712901, 2010).
psoriasis (48 papers, 2009 to 2026). An autoimmune condition characterized by red, well-delineated plaques with silvery scales that are usually on the extensor surfaces and scalp. "Background/Objectives: Baricitinib, a selective JAK1/JAK2 inhibitor, shows therapeutic potential in psoriasis; however, its oral use is associated with systemic adverse effects, encouraging the development of topical formulations." (PMID 41599117, 2025). "Here, we demonstrated that Rutin mitigated psoriasis‐associated inflammation by inactivating the JAK2/STAT3 signaling." (PMID 39167035, 2024). "JAK2 is pivotal in the signaling pathways of numerous cytokines crucial for inflammatory and immune responses; specifically, JAK2 is closely involved in the activation of the IL-23/IL-17 axis, a key pathway implicated in the pathogenesis of psoriasis." (PMID 39335596, 2024). "Polymorphisms in the JAK2 gene, including rs2274471 and rs7849191, are detected in Korean patients with psoriasis." (PMID 37893484, 2023). "Recently, polymorphisms in the JAK2 gene, including rs2274471 and rs7849191, have been detected in patients with psoriasis in the Korean population." (PMID 37893484, 2023). "Similar to A20, the association of JAK2 with psoriasis susceptibility has also been extensively studied, as JAK2 is involved in the control of cellular growth and proliferation during immune responses in these patients." (PMID 37893484, 2023). "The rs7849191 SNP is strongly associated with the rs2274471 SNP in the JAK2 gene and a decreased risk of psoriasis; however, patients carrying the rs7849191 SNP tend to develop psoriasis at a late age in the Korean population." (PMID 37893484, 2023). "Recently, risk susceptibility loci for Crohn's disease and psoriasis have been mapped at or near JAK2 and STAT3." (PMID 23372669, 2013). "Notably, rutin treatment has been shown to suppress JAK2 activation, thereby reducing psoriasis-associated inflammation and abnormal keratinocyte differentiation." (PMID 40806422, 2025). "For JAK2, the rs34536443 SNP was associated with psoriasis susceptibility." (PMID 37569685, 2023). "In addition, IL-9 is also increased in psoriasis patients, which not only promotes Th17-associated inflammation and angiogenesis in psoriasis, but also facilitates P-selectin expression and platelet activation via JAK2/STAT3 pathway in deep venous thrombosis." (PMID 37654493, 2023). "In conclusion, PLO treatment ameliorated IMQ-induced psoriasis by enhancing antioxidant defenses, and by inhibiting JAK2 and JAK3/STAT3 signaling, supporting its potential as a therapeutic candidate for psoriasis." (PMID 42306466, 2026). "Molecular docking studies targeted psoriasis-related proteins (IL-17, IL-22, IL-23, JAK2, MAPK2, NF-κB, STAT3), revealing strong binding affinities for rutin and quercetin, the extract’s dominant bioactives." (PMID 40806422, 2025). "The specificity of CBD in inhibiting JAK2, as observed in our study, suggests its potential as a targeted treatment for psoriasis and offers an alternative to currently available JAK inhibitors with broader activity profiles." (PMID 39335596, 2024). "The JAK2/STAT3 pathway is a crucial mechanism for intracellular signal transduction and is closely linked to various itching-related diseases, such as psoriasis, specific dermatitis, and nodular prurigo." (PMID 39606625, 2024). "JAK2 inhibitors are not only effective in treating psoriasis but are also used in several other skin diseases characterized by dysregulated immune responses." (PMID 39335596, 2024). "RA inhibits imiquimod-induced psoriasis-like dermatitis in mice by reducing JAK2/Stat3-dependent Th17 cell differentiation and IL-17A production." (PMID 39684446, 2024). "Several JAK2 inhibitors have been developed and are currently used in clinical practice for the treatment of psoriasis." (PMID 39335596, 2024).
psoriasis (continued). "The compound also reverted pathological changes in psoriasis-like mouse models and reduced inflammatory responses by inhibiting JAK2 and FLT3 signaling pathways." (PMID 38892253, 2024). "In a phase 1 trial, brepocitinib was well tolerated by both healthy volunteers and patients with psoriasis, but decreases in platelet and reticulocyte counts occasionally occurred and have been accounted for by some degree of Jak2 inhibition." (PMID 36834806, 2023). "Mutations in genes coding for Tyk2, Jak2, and STAT3 have been found to be associated with psoriasis." (PMID 37628670, 2023). "Similar data indicate that rosmarinic acid reduces IL-23 production, suppresses Th17-dominated inflammation, and down-regulates the Jak2/Stat3 signal pathway, suppressing psoriasis-like skin inflammation in vivo and in vitro." (PMID 37663384, 2023). "The complex pathogenesis of psoriasis is regulated by the interplay between several signaling pathways, including JAK2/STAT3 and Akt/mTOR." (PMID 36501124, 2022). "Ruxolitinib, another JAK1 and JAK2 inhibitor, has been developed as topical cream and studies in psoriasis showed a better efficacy and safety profile compared to vehicle and Non-inferior to calcipotriol-betamethasone combination." (PMID 35265634, 2022). "In this study, ADE treatment reduced the phosphorylation of JAK2/STAT3 signaling molecules in HaCaT cells and downregulated the mRNA expression of psoriasis hallmark genes." (PMID 36501124, 2022). "Baricitinib, an oral highly selective JAK1 and JAK2 inhibitor has also been studied in patients with moderate-to-severe psoriasis in Phase II trials and has shown better efficacy as compared to placebo at doses 8 mg and 10 mg." (PMID 35265634, 2022). "Tofacitinib, a TYK2 and JAK2 inhibitor developed for RA, is now making way to treatment options in other diseases such as, CD, UC, and psoriasis." (PMID 34108969, 2021). "Collectively, these findings indicate that the biotechnologically produced LV extract resolved psoriasis-like inflammation in human keratinocytes by interfering the JAK2/STAT1 signaling pathway and its effectiveness is due to its high content of RA (10%)." (PMID 33986690, 2021). "In summary, our findings demonstrate that the biotechnologically produced LV extract diminished psoriasis-like inflammation in human keratinocytes by interfering the JAK2/STAT1 signaling and its effectiveness is due to the high content of RA." (PMID 33986690, 2021). "Notable examples for targets among A35 transcripts for which drugs have been considered for treatment of psoriasis include JAK2." (PMID 33329570, 2020). "Ruxolitinib, a JAK1 and JAK2 inhibitor, has primarily been studied as a topical ointment for mild-to-moderate psoriasis, and it has been compared to other topical therapies, which include topical steroids and topical calcipotriene." (PMID 24883332, 2014). "Ruxolitinib, a JAK1 and JAK2 inhibitor, has exclusively been studied as a topical formulation for the treatment of mild-to-moderate psoriasis." (PMID 24883332, 2014). "Tofacitinib, an oral or topically administered JAK1 and JAK3 inhibitor, and ruxolitinib, a topical JAK1 and JAK2 inhibitor, have been most extensively studied in psoriasis, and both improved clinical symptoms of psoriasis." (PMID 24883332, 2014). "This is a potent JAK1 and JAK2 inhibitor that is currently under investigation for the treatment of psoriasis." (PMID 24170986, 2013). "Ruxolitinib is a JAK1/JAK2 inhibitor that is being evaluated for topical application in psoriasis." (PMID 38892253, 2024). "Rosmarinic acid attenuated imiquimod (IMQ)-induced psoriasis-like inflammation in mice by decreasing IL-23 expression, inhibiting Th17-dominated inflammation, downregulating the Janus kinase 2 (Jak2)/STAT3 signaling pathway, and inhibiting keratinocyte hyperproliferation in vivo and in vitro." (PMID 38542838, 2024).
psoriasis (continued). "Conversely, signaling of IL-12 and especially IL-23, which is pathogenetically related to psoriasis, is mediated by Tyk2/Jak2; selective inhibition of Tyk2 avoids interference with multiple Jak2 mediated pathways and potential hematopoietic or thromboembolic adverse events." (PMID 36834806, 2023). "Genome-wide association studies (GWAS) have established a relationship between the JAK-STAT pathway and IMIDs, For example, JAK2, Tyk2, STAT1, STAT3, STAT4, and IBD; TyK2, TAT1, SLE; TyK2, STAT4, RA; and TyK2, STAT3, and psoriasis are closely linked to the JAK-STAT pathway." (PMID 37351513, 2023). "More than 4500 cases and 10,000 controls were investigated in GWAS, where 7 non-HLA susceptibility loci shared by CD and psoriasis (9p24 near JAK2, 10q22 at ZMIZ1, 11q13 near PRDX5, 16p13 near SOCS1, 19p13 near FUT2, 17q21 at STAT3, 22q11 at YDJC) were found." (PMID 36443384, 2022). "Additionally, AG490, a JAK2 inhibitor, suppressed the production of psoriasis markers in cells." (PMID 36501124, 2022). "In the presence of PCs, nevertheless, the proliferation rate and number of psoriasis-like cells evidently decreased (P<0.01), accompanied with enhanced HO-1 and antioxidants, and lowered OS/inflammatory indicators as well as phosphorylated JAK2/STAT3/PI3/AKT (P<0.01)." (PMID 36178125, 2022). "However, unlike in cSCC, in which YAP functions through the AKT and ERK pathways, YAP may function through the STAT3, JAK2 and NF-κB pathways in psoriasis." (PMID 30323299, 2018). "Rutin treatment blocked the JAK2/STAT3 signaling, thus attenuating psoriasis‐related inflammation and anomalous differentiation in keratinocytes." (PMID 39167035, 2024). "JAK2/STAT3 has recently been recognized as a key inflammatory pathway in the development and pathogenesis of psoriasis." (PMID 38007430, 2023). "Overall, the application of ADE relieves psoriasis-like skin inflammation possibly by regulating the Akt/mTOR and JAK2/STAT3 signaling pathways, making it an effective alternative for psoriasis therapy." (PMID 36501124, 2022). "Overexpression of CHUK, IKBKB, NFKBIA, NFKB1, JAK2, STAT1 and STAT3, as inflammation related factors, was detected in the psoriasis model group." (PMID 34834106, 2021). "For example, IL-23, the crucial interleukin in the pathogenesis of psoriasis, transduces the signal by JAK2 and TYK2 and can be a target for the treatment of psoriasis." (PMID 34640327, 2021). "Radix arnebiae can be used both internally and externally to treat psoriasis, which decreases IL-17-induced VEGF expression by the inhibition of JAK2/STAT3 signaling and exerts an anti-inflammatory effect via proteasome inhibition." (PMID 33551804, 2020). "The JAK1/JAK2/STAT1 and JAK1/TYK2/STAT3 pathways triggered by IFN-γ and IL-22, respectively, are aberrantly activated in psoriasis, as highlighted by the peculiar STAT1 and STAT3 signatures in psoriatic skin lesions." (PMID 30581877, 2018). "Tofacitinib, a JAK1 and JAK3 inhibitor, and ruxolitinib, a JAK1 and JAK2 inhibitor, are the most extensively studied JAK inhibitors in psoriasis." (PMID 24883332, 2014). "Additionally, proteins such as MAPK3, MAPK14, JAK2, and STAT1 were identified as having a direct impact on psoriasis-related disease proteins." (PMID 39590306, 2024). "Rutin could lighten M5‐induced inflammation and abnormal differentiation in HaCaT cells by mediating the JAK2/STAT3 signaling, which offers evidence to bolster the potential of Rutin as a drug for managing psoriasis." (PMID 39167035, 2024). "Furthermore, overexpression was detected for the JAK2, STAT1 and STAT3 genes, which is in agreement with previous reports utilizing similar combinatorial stimulation used for modeling psoriasis in keratinocytes." (PMID 33986690, 2021).
psoriasis (continued). "Drug targets identified by us that are already in use for the different IMIDs include drugs that target IL1B, IL6, TYK2, and JAK2.IL1B was present in the common cell-gene network of AS, CD, psoriasis, RA, and UC, indicating a similar mechanism between these diseases." (PMID 34108969, 2021). "Moreover, inhibition of STAT3 phosphorylation by the JAK2 inhibitor WP1066 led to a marked attenuation of skin disease, demonstrating the relevance of this pathway for the development of clinical disease, further demonstrating the overlap in pathogenesis between psoriasis and the current model." (PMID 20300524, 2010). "Unlike autoimmune diseases like psoriasis or alopecia areata, where only one JAK pathway is dysregulated, AD involves increased signaling through all four JAKs (JAK1, JAK2, JAK3, and TYK2)." (PMID 40151746, 2025). "Our experimental results revealed that JAK2, STAT1 and PI3K were activated, while AKT was not influenced at a protein level in the psoriasis-like model." (PMID 34834106, 2021). "Neither JAK2 phosphorylation nor SOCS1 and SOCS3 expression was affected by HCA, suggesting that HCA-mediated suppression of PKM2-STAT3 signaling is a key event in the attenuation of psoriasis development." (PMID 33990689, 2021).